FOXD4 (forkhead box D4)
Synonyms: FREAC-5; FKHL9; FOXD4A; FREAC5
Tractability: No criterion of Open Targets' tractability assessment is met for any kind of drug.
Gene: Protein-coding gene on chromosome 9 (116,231 to 118,417, reverse strand). Ensembl gene ENSG00000170122.
Subcellular location: Nucleus
Subcellular location (Human Protein Atlas): Nucleoplasm
Gene Ontology:
Molecular function: protein binding; DNA binding, bending; DNA-binding transcription factor activity; DNA-binding transcription factor activity, RNA polymerase II-specific; RNA polymerase II cis-regulatory region sequence-specific DNA binding; sequence-specific DNA binding
Biological process: anatomical structure morphogenesis; cell differentiation; regulation of transcription by RNA polymerase II; regulation of DNA-templated transcription
Cellular component: chromatin; nucleus
Genetic constraint (gnomAD): Loss-of-function variants: 22 observed, 22.88 expected, observed/expected ratio (o/e) 0.96, 90% interval 0.69 to 1.37. The upper end of that interval is the gene's LOEUF score, 1.37, which puts it in group 5 of 6, group 1 being the genes least tolerant of losing a copy. Missense variants: 625 observed, 541.41 expected, observed/expected ratio (o/e) 1.15, 90% interval 1.08 to 1.23. Synonymous variants: 258 observed, 243.38 expected, observed/expected ratio (o/e) 1.06, 90% interval 0.96 to 1.17.
Homologues: Orthologues: chimpanzee FOXD4L4 (89% identical), mouse Foxd4 (53% identical). Paralogues in human: FOXD4L3 (81% identical), FOXD4L6 (81% identical), FOXD4L4 (80% identical), FOXD4L5 (80% identical), FOXD4L1 (69% identical), FOXD1 (32% identical), FOXD2 (30% identical), FOXD3 (28% identical), FOXE3 (25% identical), FOXC1 (22% identical), FOXE1 (22% identical), FOXC2 (22% identical), and 29 more.
Diseases named in the same sentence as FOXD4 in open-access papers:
FOXD4 is named in the same sentence as 19 diseases in open-access papers, as found by Europe PMC text mining. Sharing a sentence is not in itself a finding about the gene and the disease. The quoted sentences say what the papers report.
breast carcinoma (2 papers, 2015 to 2023). "FOXD4 and FOXD4‐Like genes (FOXD4L1, etc.)were significantly co‐expressed in 6 cancers, mostly in breast cancer, but not in their corresponding normal tissues." (PMID 37401400, 2023).
colorectal cancer (2 papers, 2020 to 2023). A primary or metastatic malignant neoplasm that affects the colon or rectum. "The value of FOXD4, FOXH1, and FOXS1 were significantly up-regulated in colorectal cancer relative to the control (FC > 1.5 and P < 0.05)." (PMID 38310407, 2023). "According to previous reports, FOXD4 induces the progression of colorectal cancer by regulating the SNAI3/CDH1 axis and can be used as a marker of colorectal cancer." (PMID 32509568, 2020).
dilated cardiomyopathy (2 papers, 2021 to 2023). Cardiomyopathy which is characterized by dilation and contractile dysfunction of the left and right ventricles. "In turn, mutation of FOXD4 on 9p24.3 is associated with dilated cardiomyopathy." (PMID 34609792, 2021). "Furthermore, mutations of FOXD4 on 9p24.3 are associated with dilated cardiomyopathy." (PMID 36672887, 2023).
Autoimmunity (1 paper, 2020). The occurrence of an immune reaction against the organism's own cells or tissues. "For example, FOXD4 have been implicated in at least four familial human diseases, and differential expression may play a role in a number of other pathologies-ranging from metabolic disorders to autoimmunity." (PMID 32509568, 2020).
cerebral palsy (1 paper, 2024). A group of disorders affecting the development of movement and posture, often accompanied by disturbances of sensation, perception, cognition, and behavior. "As protein-coding genes, chromosome 9P deletion syndrome and cerebral palsy correlate with FOXD4." (PMID 39494294, 2024).
developmental delay (1 paper, 2023). "Loss of FOXD4 in human was proposed to be responsible for developmental delay in patients with Chromosome 9p deletion (9p-) syndrome (MIM 158170)." (PMID 37697406, 2023).
head and neck cancer (1 paper, 2020). A primary or metastatic malignant neoplasm affecting the head and neck. "Kaplan–Meier analysis revealed that FOXD1, as compared to FOXD2, FOXD3 and FOXD4, upregulation more significantly (p = 0.008) predicts a poor overall survival rate in TCGA head and neck cancer patients." (PMID 32967107, 2020). "We next evaluated the prognostic significance of FOXD1, FOXD2, FOXD3 and FOXD4 in TCGA head and neck cancer patients." (PMID 32967107, 2020). "We further analyzed the transcriptional profile of FOXD1, FOXD2 and FOXD4 in the anatomic subdivision of TCGA head and neck cancer and found that the expression of FOXD2 in the hypopharynx and FOXD4 in the tonsil is relatively higher than other tissues, such as the oral cavity." (PMID 32967107, 2020). "Moreover, except FOXD3, we found that FOXD1, FOXD2 and FOXD4 are more significantly (p < 0.01) upregulated in primary tumor tissue compared to normal adjacent tissues derived from TCGA head and neck cancer patients." (PMID 32967107, 2020).
mental retardation (1 paper, 2023). "According to the literature, CER1 and FREM1 have been suggested as responsible for trigonocephaly, DOCK8 has been proposed as a candidate gene for mental retardation and seizures, FOXD4 has been related to speech and language delay, and DMRT1 may play a role in sex reversal." (PMID 36672887, 2023).
oral cancer (1 paper, 2020). "Robustly, FOXD1, but not FOXD2, FOXD3 and FOXD4, was significantly (p < 0.01) upregulated in primary tumors compared to normal adjacent tissues derived from oral cancer patients deposited in the GSE42743 dataset." (PMID 32967107, 2020).
tumor (6 papers, 2020 to 2025). "FOXD4 participated in immune system regulation, tumor progression, and metastasis by methylation modification." (PMID 33552157, 2021). "For example, FOXD4 was enriched in pathways related to signal transduction and transcriptional regulation, suggesting that it may play an important role in tumor signaling and gene expression regulation." (PMID 39494294, 2024). "In TIME-1, FOXD4 was marked as epigenetically silenced in 85% of the cases, and its methylation silencing may lead to immune system dysfunction and tumor proliferation." (PMID 33407585, 2021). "Additionally, we found that essential passenger genes, including NOP2, DCTN6 and FOXD4, were associated with closed chromatin and increased DNA methylation at the same respective loci when amplified compared to when not amplified in tumor PDCs compared to normal PDCs." (PMID 40931149, 2025). "After we identified that the expression of three FOX genes (FOXD4, FOXH1, and FOXS1) are independent prognostic factors and regulate tumor immunity in COAD, we investigated the Spearman’s correlation of these three genes with various cancer-associated pathways activity (R > 0.20 and P < 0.01)." (PMID 38310407, 2023). "However, the FOXD4 level was not related to the tumor immunity in the COAD (Spearman correlation test, R > 0.20, P < 0.01)." (PMID 38310407, 2023).
cancer (5 papers, 2018 to 2023). A tumor composed of atypical neoplastic, often pleomorphic cells that invade other tissues. "LHX1 ChIP-seq data in differentiated P19 carcinoma cells shows a low confidence peak ∼1k bp upstream of the Foxd4 transcriptional start site (TSS)." (PMID 35178396, 2021). "In addition, we investigated the expression variation of these prognostic markers in cancers using the Oncomine database and GSE166427, and found consistent results which ultimately indicate the substantial roles of FOXD4, FOXH1, and FOXS1 incolon cancer." (PMID 38310407, 2023).
immune dysfunction (2 papers, 2021 to 2024). "Besides, the FOXD4 methylation was also associated with the immune dysfunction and cell proliferation." (PMID 33407585, 2021). "Additionally, FOXD4 methylation is associated with immune dysfunction and cell proliferation." (PMID 39494294, 2024).
kidney disease (1 paper, 2020). "However, whether FOXD3/FOXD4 related to kidney disease remains unclear and needs further investigation." (PMID 33274190, 2020).
FOXD4 also shares sentences with these, for which no sentence is quoted: colonic cancer (1 paper); gastric cancer (1); metabolic disorders (1); myeloma (1); obsessive-compulsive disorder (1); trigonocephaly (1).